METTL16 (methyltransferase 16, RNA N6-adenosine)
Diseases named in the same sentence as METTL16 in open-access papers (continued):
Sharing a sentence is not in itself a finding about the gene and the disease.
METTL16 also shares sentences with these, for which no sentence is quoted: ovarian cancer (3 papers); osteosarcoma (2); arteriovenous malformation (1); atherosclerosis (1); blood cancer (1); brain cancer (1); breast invasive carcinoma (1); breast tumors (1); cervical squamous cell carcinoma (1); chronic hepatitis B (1); clear cell renal carcinoma (1); colon adenocarcinoma (1); colon cancer (1); colorectal (1); Dystonia (1); endocervical adenocarcinoma (1); gastric tumors (1); head and neck squamous cell carcinoma (1); Insulin resistance (1); kidney chromophobe (1); lung squamous cell carcinoma (1); mastitis (1); Oral Squamous Cell Carcinoma (1); osteoarthritis (1); premature ovarian failure (1); prostate adenocarcinoma (1); soft tissue sarcoma (1); uterine corpus endometrial carcinoma (1).